SVEP1 (sushi, von Willebrand factor type A, EGF and pentraxin domain containing 1)
Diseases named in the same sentence as SVEP1 in open-access papers (continued):
Sharing a sentence is not in itself a finding about the gene and the disease.
airway hyperresponsiveness (1 paper, 2022). "In the airway, ligation of integrin α9β1 can prevent GPCR‐mediated airway hyperresponsiveness, a phenotype comparable to the vascular role for integrin α9β1 and SVEP1 identified here." (PMID 35802072, 2022).
Alzheimer disease (1 paper, 2024). A progressive, neurodegenerative disease characterized by loss of function and death of nerve cells in several areas of the brain leading to loss of cognitive function such as memory and language. "Additionally, SVEP1—an immunologically relevant cellular adhesion protein—has been causally linked to Alzheimer’s disease and multiple forms of cardiovascular disease and has been prominently associated with increased age." (PMID 38438772, 2024).
bladder cancer (1 paper, 2019). "Genes such as COL5A2, SVEP1, NID2, and MMP23B were responsible for the growth of many cancer types such as bladder cancer and mammary adenocarcinoma, but these genes may be involved in the pathogenesis of GBM." (PMID 31137733, 2019).
colorectal cancer (1 paper, 2025). A primary or metastatic malignant neoplasm that affects the colon or rectum. "A recent study reported that silencing SVEP1 activates the PI3K/AKT pathway, promoting colorectal cancer progression." (PMID 41315239, 2025).
congenital glaucoma (1 paper, 2022). "We did not identify pathogenic or likely pathogenic variants in other genes known to cause congenital glaucoma, including rare variants (allele frequency <0.001) in ANGPT1, CPAMD8, CYP1B1, MYOC, LTBP2, PITX2, SVEP1, and TEK." (PMID 36453543, 2022). "Genetic disruption of SVEP1, a large ECM protein expressed in the TM, has been shown to cause a severe congenital glaucoma phenotype in mice." (PMID 36453543, 2022).
endotoxemia (1 paper, 2020). "According to a study evaluating the environments of endotoxemia using human umbilical vein endothelial cells, the expression of SVEP1 was significantly upregulated in a human cell culture model of endotoxemia." (PMID 32678854, 2020).
hearing loss (1 paper, 2022). "Compound heterozygous variants of SVEP1 were identified as the candidate cause of the sporadic hearing loss in two families: 1535 and 1555." (PMID 35248088, 2022). "The other five genes (SVEP1, CACNG1, GTPBP4, PCNX2, and TBC1D8) were categorized as Tier 4 genes, with no known association with hearing loss." (PMID 35248088, 2022).
Hirschsprung disease (1 paper, 2023). Hirschsprung disease (HSCR) is a congenital intestinal motility disorder that is characterized by signs of intestinal obstruction due to the presence of an aganglionic segment of variable extent in the terminal part of the colon. "The rs192347509 of SVEP1 was identified in two Short segment Hirschsprung disease patients." (PMID 37372431, 2023).
leukemia (1 paper, 2021). A malignant (clonal) hematologic disorder, involving hematopoietic stem cells and characterized by the presence of primitive or atypical myeloid or lymphoid cells in the bone marrow and the blood. "Molecular mimics of SVEP1 could be used therapeutically to enhance myelopoiesis, and inhibitors of SVEP1 binding to HSPC could be used to treat myeloproliferative disorders and leukemia." (PMID 35174156, 2021).
liver diseases (1 paper, 2022). "Our research shows that SVEP1 may be not a promising biomarker for the diagnosis of HBV-related liver diseases at different stages, because its expression is just higher than the HCs group." (PMID 36002595, 2022). "SVEP1 expression may be one of universal markers for HCC and liver fibrosis, but it is not classify HBV-related liver diseases at different stages." (PMID 36002595, 2022).
lymphedema (1 paper, 2022). Excess fluid collection in tissues, causing swelling. "SVEP1 is a large extracellular mosaic protein with functions in protein interactions and adhesion, and its mutations have been found by a recent study in lymphedema patients." (PMID 35806420, 2022).
myeloid leukemia (1 paper, 2021). A clonal proliferation of myeloid cells and their precursors in the bone marrow, peripheral blood, and spleen. "In future it will be very important to investigate more fully the expression and function of SVEP1 by human bone marrow and spleen stromal subsets, and to determine whether changes in SVEP1 expression is associated with myeloid leukemias or myeloproliferative disorders." (PMID 35174156, 2021).
oral diseases (1 paper, 2023). "The presence of SVep1 may confer immunity to S. vestibularis against infection by related phages and holds potential for being engineered as a genetic tool to regulate oral microbiome homeostasis and oral diseases." (PMID 37779698, 2023).
Ovarian cyst (1 paper, 2020). The presence of one or more cysts of the ovary. "It should be noted that several members of family 8 shared additional nonocular clinical features, such as Perthes disease and ovarian cysts, which may also be related to abnormal SVEP1 and/or TEK signaling." (PMID 33027505, 2020).
Parkinson disease (1 paper, 2022). A progressive degenerative disorder of the central nervous system characterized by loss of dopamine producing neurons in the substantia nigra and the presence of Lewy bodies in the substantia nigra and locus coeruleus. "Previous MR studies on Alzheimer’s disease suggest potential causal associations with BIN1, CCL27, C3, CD33, CD4 T cells, GDF-15 and SVEP1, whereas MR studies on Parkinson’s disease suggest a potential causal association with GPNMB, IL-6 and MIP1b." (PMID 37118290, 2022).
preeclampsia (1 paper, 2022). Preeclampsia is a hypertensive disorder of pregnancy that is characterized by new-onset hypertension with proteinuria presenting after 20 weeks of gestation, and depending on mild or severe forms may initially present with severe headache, visual disturbances, and hyperreflexia. "Intriguingly, Svep1 mRNA is also strongly downregulated in cytotrophoblast populations in preeclampsia." (PMID 35312765, 2022).
cancer (13 papers, 2013 to 2025). A tumor composed of atypical neoplastic, often pleomorphic cells that invade other tissues. "Two possible markers of cancer-associated fibroblasts (CAFs), MFAP5 and SVEP1, were upregulated in biopsies, and the expression of the last one was positively correlated with a longer OS." (PMID 39202425, 2024). "SVEP1 is an important cell adhesion molecule, regulating intercellular adhesion, with implications for carcinoma progression." (PMID 35197508, 2022). "The cell adhesion molecule SVEP1 can induce EMT and associated with disseminating cancer cells to secondary organ." (PMID 31272500, 2019). "However, the exact role of aberrant interactions between SVEP1 and integrin α9β1 in cancer development remains poorly understood, necessitating further elucidation." (PMID 41315239, 2025). "Therefore, understanding the roles of SVEP1 and its interactors in cancer is crucial for leveraging its prognostic and therapeutic potential." (PMID 41315239, 2025). "Our findings revealed that the SVEP1 levels were reduced in 18 of the 24 cancer types." (PMID 41315239, 2025). "The related role of SVEP1 in cancers was first reported in 2007." (PMID 36699464, 2022). "We identified SVEP1 expression by analyzing 220 HCC samples from our cancer center." (PMID 32371982, 2020). "However, the expression patterns and functional roles of SVEP1 in other cancer histotypes, including ICC, remain unclear." (PMID 41315239, 2025). "However, the function and mechanisms of SVEP1 in malignant tumor progression remain largely unknown." (PMID 32371982, 2020). "Our study revealed SVEP1 as an independent prognostic factor for ICC, elucidating its role in regulating the malignant progression of this cancer." (PMID 41315239, 2025). "The levels of several mRNAs that code for surface proteins with roles in cancer were similarly upregulated, including ALK, PTPRM, PTPRF, PTPRK, and SVEP1." (PMID 39335212, 2024). "We then screened 12 hub genes from the blue module based on MM and GS, such as PODN, DCN, CCDC80, SVEP1 and AEBP1, which were reported to be predictive biomarkers and correlated with immune infiltration in various cancers." (PMID 36768989, 2023). "Accordingly, miR-1269b can affect the progression of cancer by targeting downstream genes (METTL3, CDC40, SVEP1, and PTEN)." (PMID 35252180, 2022). "It is noteworthy to mention that the cancer patient was graded to be metastatic whereas two of the candidate genes (SORD and SVEP1) were able to induce EMT." (PMID 31272500, 2019). "It is noteworthy that by focusing on DEGs enriched in the adhesion-related pathway, we found a highly differentially expressed gene, SVEP1, which has not been previously reported in cancer." (PMID 32371982, 2020). "In addition, miR-1269b can also affect the progress of cancer through a series of regulatory methods, such as directly targeting the downstream gene METTL3 or by targeting SVEP1 and PTEN to drive the PI3K/AKT signaling pathway, thereby mediating tumor recurrence and metastasis." (PMID 35252180, 2022). "However, another remarkable DEG, SVEP1, was identified, and its role in cancer metastasis has never been explored." (PMID 32371982, 2020). "However, the role of SVEP1 in cancer progression has never been reported before." (PMID 32371982, 2020).
tumor (10 papers, 2018 to 2025). "While TBIL, SN, and tumor thrombus align with previous literature, our study is the first to identify low-SVEP1 expression as an independent risk factor for DFS and OS in ICC." (PMID 41315239, 2025). "Subsequently, the clinical analysis indicated that the decreased expression of SVEP1 in tumor tissues was an independent risk factor for the prognosis of ICC (DFS, p = .017; OS, p = .040)." (PMID 36699464, 2022). "The multivariate analysis showed that elevated serum alpha-fetoprotein levels (≥20 ng/ml) and decreased expression of SVEP1 in tumor tissues were two independent risk factors for the prognosis of HCC." (PMID 32371982, 2020). "Additionally, TBIL ≥ 21 μmol/L (p = 0.009), positive tumor thrombus (p = 0.005), and low-SVEP1 expression (p < 0.001) were considered independent risk factors for OS." (PMID 41315239, 2025). "Given the decreased SVEP1 expression in most ICC tumor tissues and its association with poor prognosis, we examined the correlation between SVEP1 expression and other known ICC risk factors associated with short DFS or OS, such as tumor size, lymph node (LN) metastasis, and serum CA19-9 levels." (PMID 41315239, 2025). "To validate the expression pattern of SVEP1 in ICC, we selected three additional ICC cohorts from our center and analyzed SVEP1 expression and localization in paired tumors and corresponding para-tumor tissues using RT-PCR and IHC staining." (PMID 41315239, 2025). "SVEP1 downregulation in CCA tumor tissues was significantly more pronounced than that in the corresponding para-tumor tissues in TCGA (paired, n = 9) and GSE119336 (paired, n = 15) databases." (PMID 41315239, 2025). "To address this knowledge gap, we analyzed SVEP1 mRNA levels across 24 tumor histotypes using TCGA database." (PMID 41315239, 2025). "Then, we further verified that the expression of SVEP1 in the tumor tissues was substantially lower than that in the adjacent normal tissues by using western blot assay in five paired ICC samples." (PMID 36699464, 2022). "Then, a gene set enrichment analysis (GSEA) based on the mRNA data of the ICC samples from GSE132305 was performed to validate the correlation of the SVEP1 mRNA level and tumor cell proliferation phenotype." (PMID 36699464, 2022). "More importantly, in our previous studies, we found and reported that SVEP1 also plays a critical role in tumor heterogeneity, proliferation and metastasis, and tumor stem cell-like phenotype maintenance." (PMID 36699464, 2022). "In contrast, only 13 out of 33 (39.4%) cases with a tumor diameter <3 cm had low SVEP1 expression levels (p = 0.049)." (PMID 32371982, 2020). "The results confirmed that SVEP1 expression was dramatically downregulated in tumor tissues compared with para-tumor tissues (p < 0.0001), and 114 out of 207 tumor tissues (55.07%) had low SVEP1 expression levels." (PMID 32371982, 2020). "We found that the expression level of SVEP1 was closely correlated with tumor size and satellite nodule occurrence (p = 0.049, p = 0.007)." (PMID 32371982, 2020). "We found that compared with the control group, the SVEP1-knockdown group had dramatically accelerated tumor growth and markedly formed larger and heavier tumor nodules (p < 0.0001)." (PMID 32371982, 2020). "Next, we chose four pairs of HCC samples to subject to western blot (WB) and verified that the SVEP1 expression in the HCC tissues was substantially lower than that in the para-tumor tissues." (PMID 32371982, 2020). "Based on these findings, we hypothesized that SVEP1 depletion in ICC contributes to the loss of the cellular epithelial phenotype and promotes tumor progression and metastasis in vivo." (PMID 41315239, 2025). "Furthermore, IHC staining of a tissue microarray comprising 113 cases revealed a significant decrease in SVEP1 expression in most ICC tumor tissues (p < 0.0001), with positive SVEP1 expression primarily observed in the cytoplasm and ECM." (PMID 41315239, 2025).
tumor (continued). "Moreover, the expression of SVEP1 was negatively correlated with the proportion of abnormal neovascularization in the tumor microenvironment of the ICC." (PMID 36699464, 2022). "In summary, these results suggested that decreased expression of SVEP1 might be an important link of intra-tumor abnormal neovascularization in ICC." (PMID 36699464, 2022). "Moreover, the expression level of SVEP1 decreased significantly in tumor tissues compared with paired adjacent normal tissues (p < .0001)." (PMID 36699464, 2022). "In addition, SVEP1 has been proven to play an important role in preventing tumor cells from invading bone niches as a key cell adhesion molecule." (PMID 36699464, 2022). "In this study, we verified that the expression level of SVEP1 was dramatically decreased in the ICC tumor tissues when compared with the corresponding adjacent tissues and that it was negatively correlated with OS and DFS by using IHC in a 47 ICC patient tissue microarray." (PMID 36699464, 2022). "Taken together, these results suggest that a low level of SVEP1 expression is a critical feature of HCC that might pave the way for tumor proliferation and metastasis." (PMID 32371982, 2020). "We hypothesize that SVEP1 could be used as a promising biomarker for the prediction of tumor progression and recurrence for the clinicopathological diagnosis of HCC." (PMID 32371982, 2020). "However, whether SVEP1 participates in the process of tumor cell phenotype switching remains unknown." (PMID 41315239, 2025). "Next, we further investigated the role of SVEP1 in regulating ICC cell differentiation and phenotype transition, as well as mediating tumor progression and metastasis using ICC PDOs and PDX models." (PMID 41315239, 2025). "Downregulated SVEP1 expression promoted ICC cell proliferation, chemotactic migration, and invasion in vitro, as well as tumor growth and lung metastasis in vivo." (PMID 41315239, 2025). "Downregulation of SVEP1 expression promoted in vitro HCC cell migration, chemotaxis, invasion and proliferation, as well as in vivo tumor growth, local invasion and metastasis in a mouse model." (PMID 32371982, 2020). "Among downregulated genes, some have tumor suppressive activities, e.g., FBLN2, LYPD1, SVEP1." (PMID 41469472, 2025). "We were able to rule out that FCER1A or SVEP1 is involved in the observed tumor dormancy-inducing activity of PEAR1." (PMID 41185039, 2025). "First, we detected SVEP1 expression in HCC cell lines with different malignant potential and found that SVEP1 expression was the highest in Hep3B, which is known as a low-grade malignant tumor cell line." (PMID 32371982, 2020). "Thus, we propose that when FOXI3 in tumor cells modulate the secretion of other bone factors including SPOCK1, Dlx, MAF, PthrP, HAS2, SVEP1, TGFβ3, and FGF which further primes the microenvironment, creates a crosstalk to help tumors grow in the bone." (PMID 30018953, 2018). "In this study, we verified that the expression level of SVEP1 was significantly reduced in HCC tumor tissues and negatively correlated with HCC patient OS and DFS by using a large-scale HCC tissue microarray and bioinformatics analysis of online-public databases." (PMID 32371982, 2020).
cardiovascular disease (3 papers, 2023 to 2024). "Sushi, von Willebrand factor type A, EGF and pentraxin domain containing 1 (SVEP1) is an extracellular matrix protein that causally promotes cardiovascular disease in humans and mice." (PMID 38370227, 2024). "Similarly, genetically encoded changes in plasma concentrations of both proteins were positively associated with risk of cardiovascular disease (SVEP1 P = 4.5 × 10−12; PEAR1 P = 0.0051)." (PMID 36792666, 2023). "SVEP1 and PEAR1 causally and concordantly relate to platelet phenotypes and cardiovascular disease in humans, as determined by Mendelian Randomization." (PMID 36792666, 2023). "Here, the authors identify SVEP1 as a ligand for the orphan receptor PEAR1 and provide insight into the role of this interaction in cardiovascular disease." (PMID 36792666, 2023).
kidney (1 paper, 2023). "Accordingly, we assume that the inhibition of the degradation of SVEP1 gene products using products may offer a therapeutic strategy to prevent kidney transplant rejection." (PMID 37372431, 2023).
SVEP1 also shares sentences with these, for which no sentence is quoted: heart failure (2 papers); infection (2); intrahepatic cholangiocarcinoma (2); non-small cell lung carcinoma (2); angiosarcoma (1); Brain atrophy (1); cardiac dysrhythmias (1); colon cancer (1); COVID-19 (1); cutaneous melanoma (1); dengue (1); essential hypertension (1); liver fibrosis (1); liver neoplasm (1); lung adenocarcinoma (1); mammary adenocarcinoma (1); metabolic disorders (1); myeloproliferative disorder (1); neutropenia (1); Obesity (1); ovarian carcinoma (1); Perthes disease (1); pulmonary hypertension (1); respiratory failure (1).